EPHB3 (EPH receptor B3)
Diseases named in the same sentence as EPHB3 in open-access papers (continued):
Sharing a sentence is not in itself a finding about the gene and the disease.
tumor (continued). "CDH1 and EPHB3 are essential for an intact tissue architecture of the intestinal epithelium and possess tumor suppressor activity." (PMID 29155818, 2017). "In CRC, the tumor suppressor gene EPHB3 was shown to promote cellular adhesion and to prevent tumor cell spreading." (PMID 29155818, 2017). "Ephb3−/− in the ApcMin/+ mice leads to conversion of 47% of tumours to adenocarcinoma, whilst ΔcyEphb2 deletion in the ApcMin/+ model reduces the number of tumours formed, but those tumours exhibit increased invasion." (PMID 26414675, 2016). "Another gene, EphB3, corresponds to a receptor of the ephrin signaling pathway, a cascade whose deregulation contributes to tumor cell shape, adhesion, migration and angiogenesis." (PMID 19337376, 2009). "We also note > two-fold increased expression in some members of the Ephrin pathway (EPHA10, EPHB1, EPHB2, EPHB3) that may play key roles in tumor progression, invasion, and immune evasion." (PMID 38704802, 2024). "The end-result is that EPHB3 signaling promotes tumor-suppressive processes." (PMID 35269901, 2022). "Moreover, silencing of EphB3 significantly affected cycle progression distribution and increased apoptosis in CRC cell which revealed that knockdown of EphB3 inhibited tumor growth." (PMID 34959648, 2021). "As E-cadherin is frequently downregulated in budding cells and is a crucial step that promotes tumor invasion and metastasis, we investigated whether EPHB3 influences E-cadherin expression and vice versa." (PMID 32294981, 2020). "For example, the correlation of CDH1 mutations to the activation of WNT, EGFR, and AKT pathways as well as the inactivation of tumor suppressors, such as EPHB3 and IGSF8, provides several hypotheses to test." (PMID 29520031, 2018). "Rather, we observed an ~40‐fold increase in tumour number together suggesting changes in EPHB3 stabilisation are not the primary cause of tumour initiation following Huwe1 deletion." (PMID 28003334, 2017). "We identified a group of CTNNB1/TCF target genes that are activated in the absence of TCF7L1, including EPHB3, a marker of Paneth cell differentiation that has also been implicated as a tumor suppressor in CRC." (PMID 27333864, 2016). "Likewise, A-type receptor expression is restricted to tumor cells and B-type receptor expression is considerably higher in, or selective for, tumor cells, the latter exemplified by EPHB3 and EPHB4." (PMID 27215396, 2016). "Interestingly, in patients with gastrointestinal tumors, it has been found that the expression of genes, such as TLRs, WFDC2, TTLL12, THRA, and EPHB3, which can trigger an immune response and release of pro-inflammatory factors and thus accelerate tumor cell invasion, is disturbed." (PMID 38243957, 2025). "Besides, rescue experiments demonstrated that strengthening EPHB3 could partly reverse proliferation, migration, and invasion capabilities of tumor cells induced by miR-637 upregulation and exhibit regulative effects on GC." (PMID 35027539, 2022). "The inhibition of EphB3 expression resulted in reduced ESCC cell proliferation, migration, invasion, and tumor growth via the dysregulation of the epithelial-mesenchymal transition process." (PMID 39196978, 2024). "In addition, the knockdown of YTHDF2 and EPHB3 or the knockdown of YTHDF2 and TNFAIP3 promoted the tumor growth in xenograft model under TMZ treatment compared with YTHDF2 silence alone." (PMID 35582627, 2022). "KRAS-Mut tumors showed significant upregulation of tumor migration (TGFBR2-S553 and EPHB3) and PI3K/AKT activation (PIP4K2C and PIK3R1), while the KRAS-WT group was enriched in immune regulation (TAP1/2, IFITM1, and IFIH1-S301) and cellular metabolism (DGAT1 and HINT3)." (PMID 35836817, 2022). "Both the EPHB3 and TNFAIP3 are the typical tumor suppressors." (PMID 35582627, 2022).
tumor (continued). "In a large cohort of CRC patients, EPHB3 positivity was observed in 24% of 610 CRCs and was negatively correlated with tumor differentiation, lympho-vascular invasion, and tumor, node, and metastasis stages." (PMID 32294981, 2020). "The mRNA levels of c-myc, Birc5, Cd44, Lgr5, Tcf7, Mmp7, and Ephb3 were significantly increased in tumor area compared with non-tumor area." (PMID 28710436, 2017). "Moreover, FOXA1, FOXA2, and FOXA3 were also grouped together with the tumor/invasion suppressor genes EPHB2 and EPHB3, and with the intestine-specific differentiation genes CDX1 and CDX2 (cluster 2)." (PMID 29155818, 2017). "However, an increase of EphB3 expression in tissues that do not normally express this gene, such as the lung, appears to promote oncogenic transformation and tumor development." (PMID 30944407, 2019). "Three genes - CHEK1, EPHB3, and PIP5K1A - were increased at least 2 fold in expression in more than 50% of the tumor set compared to non-cancer controls." (PMID 25474241, 2014).
cancer (24 papers, 2008 to 2024). A tumor composed of atypical neoplastic, often pleomorphic cells that invade other tissues. "Loss of EPHB3 expression was frequently observed in budding cancer cells at the invasive front of CRC tumors, and this loss appears to precede E-cadherin downregulation." (PMID 32294981, 2020). "Cancer budding, a risk factor for metastasis and worse prognosis, is frequently detected at the invasive front of CRCs, thus we sought to determine whether EPHB3 expression is altered in the budding cells." (PMID 32294981, 2020). "The association between these three genes, EGF, EPHB3, and POTEF, and Run Variance indicates their roles in the heterogeneous colonization of cancer cells." (PMID 38811597, 2024). "Tyrosine kinase-signaling genes, EPHB3, SH3TC2, and GRB7, which are associated with poor disease-free survival and promote cancer progression and invasion, were downregulated by DIM–AHR." (PMID 37834026, 2023). "This in turn would further enhance the understanding of the exact functions of the receptor and offer potential therapeutic agents for several cancer disorders related to EphB3." (PMID 34959648, 2021). "Despite these finding, the exact role of EphB3 in cancer remains controversial since some reports have documented conflicting roles of EphB3 in carcinogenesis." (PMID 34959648, 2021). "EPHB3 expression was higher in CRCs than in normal mucosa and was associated with the intestinal stem cell markers EPHB2, OLFM4, LRIG1, and a proposed cancer stem cell marker, CD44." (PMID 32294981, 2020). "EPHB3 protein levels were also higher in cancer tissues than in matched normal tissues in all five cases examined." (PMID 32294981, 2020). "As phosphoinositide-3-kinase–protein kinase B/AKT (PI3K-PKB/AKT) and mitogen-activated kinase (MAPK) signaling pathways are often involved in cancer cell proliferation, we examined the impact of EPHB3 expression on the activation of the AKT and ERK proteins." (PMID 32294981, 2020). "We also evaluated EPHB3 expression in a colitis-associated cancer (CAC) model, and its effects on cancer growth and migration were assessed using CRC cell lines." (PMID 32294981, 2020). "In each cancer type, we identify combinations of mutated genes that overlap known cancer pathways and also contain potentially novel cancer genes including IL7R and the EphB receptor EPHB3 in STAD, and the scavenger receptor SRCRB4D in GBM." (PMID 26253137, 2015). "Fibroblasts express high ephrin-B2, which activates EphB3/EphB4 in cancer cells." (PMID 38730588, 2024). "This study suggests that direct contact between CAFs and cancer cells promotes PCa invasiveness and this hypothesis is supported by the high expression in advanced human PCa of EphB3/4 and EphrinB2 in epithelial and stromal cells, respectively." (PMID 32668821, 2020). "As expected, in budding cancer cells both EPHB3 and E-cadherin expression were downregulated." (PMID 32294981, 2020). "However, the exact role of EphB3 in cancer remains ambiguous." (PMID 34959648, 2021). "EphB3 and EphB2 are reported to be overexpressed in GBM cell lines and to have a pro-tumoral role promoting migration and invasion in cancer cells." (PMID 32764266, 2020). "As CD44 only showed a positive correlation with EPHB3 among the candidate CSC markers we examined, it would be interesting to explore the interplay between CD44 and EPHB3 and its effect on cancer stem cell biology in CRCs in future studies." (PMID 32294981, 2020). "There were some RTK genes (EPHB6, EPHA1, EPHB3, FGFR4, PDGFRB, and FLT4) showing amplification in cancer cells." (PMID 32038722, 2019). "Collectively, ephrin-B2 and EphB3/4 may not mediate physical adhesion between cancer cells and fibroblasts but probably contribute to the co-invasion of the two cell types by inhibiting CIL after their interaction." (PMID 38730588, 2024). "Additionally, no studies have comprehensively assessed the changes in EPHB3 expression from benign to malignant tumors of the colorectum." (PMID 32294981, 2020).
cancer (continued). "Several other molecules, including CD44, CD133, CD24, and CD166 are potential cancer stem cell markers that may contribute to CRC progression and metastasis; therefore, we assessed if their expression correlated with that of EPHB3 in the CSC samples and controls." (PMID 32294981, 2020).
infection (9 papers, 2013 to 2025). The state of being infected such as from the introduction of a foreign agent such as serum, vaccine, antigenic substance or organism. "We identify EphA4 and EphB3 as direct interaction partners of the MHV68 gH/gL complex that facilitated MHV68 infection in different cell types from humans and mice." (PMID 40501621, 2025). "In agreement with reduced infection of Eph- and Plxdc-binding virus mutants on HaCaT cells, EPHB3 and PLXDC2 expression was detected in HaCaT cells in published datasets (GSE95080, GSE138800) and by confirmatory qPCR of our samples." (PMID 33657166, 2021). "Furthermore, the infection of LV‐YTHDF2 in T98G and LN229 cells reduced the luciferase activity of EPHB3‐WT (with m6A sites), and the infection of LV‐sh‐YTHDF2 in T98G/TR cells and LN229/TR cells increased the luciferase activity of EPHB3‐WT." (PMID 35582627, 2022). "Some proteins were degraded throughout early infection, whereas others including ephrin receptor B3 (EPHB3) were most significantly degraded during a more limited interval, which may reflect the kinetics of expression of the HCMV proteins that target them." (PMID 30122656, 2018). "Nuclear accumulation of the viral genome in HUVEC four hours post infection was significantly reduced by 74% in the presence of 5 μg/ml EphB3-Fc, whereas nuclear delivery to fibroblasts may have been reduced slightly but the difference was not significant." (PMID 23696734, 2013). "Ectopic expression of EphB3 of human and mouse origin exhibited the strongest enhancement of MHV68 ORF59-GFP infection, leading to an ~20-fold increase in GFP+ cells." (PMID 40501621, 2025). "Indeed, when Raji cells were engineered to express high amounts of the fusion receptor EphB3 through lentiviral transduction, RRV infection occurred independently of vesicle acidification as demonstrated by resistance to Bafilomycin A1 treatment (filled circles)." (PMID 39820197, 2025). "Ectopic expression of EphB3 of human and mouse origin exhibited the strongest enhancement of MHV68 ORF59-GFP infection, leading to an ~ 20-fold increase in GFP+ cells.Expression of EphA4 had a comparably less pronounced effect on MHV68 infection of ~8-fold enhancement compared to empty vector." (PMID 41118409, 2025). "However, both the LV‐YTHDF2 and LV‐sh‐YTHDF2 infections exerted no significant influence on the luciferase activity of EPHB3‐Mut (with mutant m6A sites)." (PMID 35582627, 2022). "Contrarily, we observed no influence of saturating concentrations of EphA2-Fc/EphB3-Fc on the infection with Eph-binding-negative mutants KSHV gH-ELAAN, RRV gH-AELAAN or RRV ΔgL when compared to infection with untreated or soluble Fc treated viral inocula." (PMID 29432452, 2018). "Interestingly, differences in binding affinity of EphA4 and EphB3 observed in co-precipitation and ELISA experiments did not correlate with augmentation of MHV68 infection of Raji cells." (PMID 40501621, 2025). "Interestingly, differences in apparent saturation binding of EphA4 and EphB3 observed in co-precipitation and ELISA experiments did not correlate with augmentation of MHV68 infection of Raji cells." (PMID 41118409, 2025). "While preincubation with EphB3-Fc did not reduce RRV-YFP gH-AELAAN infection, preincubation with either hPlxdc2-FcStrep or a combination of hPlxdc2-FcStrep and hEphB3-Fc reduced infection by ~50% as observed for RRV-YFP wt infection (right column group)." (PMID 33657166, 2021).
adenocarcinoma (2 papers, 2017 to 2021). A common cancer characterized by the presence of malignant glandular cells. "Gene amplifications of 3q including SOX2, TP63, PIK3CA, and EPHB3 were observed in as many as 86% of SQC samples but only 21% of adenocarcinoma samples." (PMID 28591695, 2017).
EPHB3 also shares sentences with these, for which no sentence is quoted: injury (2 papers); invasive carcinoma (2); lung squamous cell carcinoma (2); melanoma (2); autism (1); bleeding disorder (1); brain tumors (1); central nervous system diseases (1); colorectal adenocarcinoma (1); depression (1); dysplasia (1); experimental autoimmune encephalomyelitis (1); frontonasal dysplasia (1); gastrointestinal tumors (1); hepatocellular carcinoma (1); hyperplastic polyp (1); lung adenocarcinoma (1); medullary sponge kidney disease (1); meningioma (1); microphthalmia (1); osteosarcoma (1); sarcoma (1); soft tissue neoplasm (1); synovial sarcoma (1); tubular adenoma (1).